HNF4A (hepatocyte nuclear factor 4 alpha)
Diseases named in the same sentence as HNF4A in open-access papers (continued):
Sharing a sentence is not in itself a finding about the gene and the disease.
Sepsis (continued). "Therefore, it is postulated that the down-regulation of HNF4A may potentially play a role in the pathogenesis of sepsis-associated pulmonary damage by modulating the phenotype transition of macrophages." (PMID 39979267, 2025). "Therefore, we hypothesize that HNF4A may exert a regulatory role in the sepsis-associated lung injury by influencing NCOA2/GR-mediated gene transcription." (PMID 39979267, 2025). "Collectively, these results suggested that lung tissues are severely damaged after CLP-induced sepsis, mainly manifested as pulmonary edema and inflammatory cell infiltration, and HNF4A levels are down-regulated." (PMID 39979267, 2025). "Targeting HNF4α with the agonist N-trans caffeoyl tyramine (NCT) provided protection in sepsis, both prophylactically and therapeutically, by enhancing HNF4α chromatin binding and promoting the expression of its target genes." (PMID 40904458, 2025). "Then, we established a mouse sepsis model through a cecal ligation and puncture method and observed that the expression of HNF4A was reduced in both lung tissues and alveolar macrophages." (PMID 39979267, 2025). "By analyzing a CLP-induced microarray of gene expression in lung tissue of sepsis mice, we found that a notable reduction in the expression of HNF4A." (PMID 39979267, 2025). "In this study, we observed diminished HNF4A expression in the lung tissues in a murine model of sepsis." (PMID 39979267, 2025). "We previously reported that HNF4α progressively loses its function in the liver during sepsis, driven by reduced chromatin binding, leading to decreased H3K27 acetylation (H3K27ac) and, to a lesser extent, altered chromatin accessibility." (PMID 40904458, 2025). "In conclusion, this research validates the potential protective effect of HNF4A against lung injury in sepsis." (PMID 39979267, 2025). "Nevertheless, these results indicate that both reduced Nr1i3 mRNA expression and impaired CAR DNA binding contribute to the diminished CAR transcriptional activity observed during sepsis, and that both mechanisms are affected by HNF4α." (PMID 40904458, 2025). "The administration of HNF4A-overexpressed adenoviral particles in mice raised the expression of HNF4A in the lung and reduced the sepsis-induced mortality." (PMID 39979267, 2025). "Despite Hnf4a mRNA downregulation in sepsis, total protein levels and the percentage of HNF4α-positive nuclei remained unchanged." (PMID 39261648, 2024). "Hepatic HNF4α LOF during sepsis, attributed to reduced chromatin binding, has implications for lipid metabolism and IL6-mediated APR downstream." (PMID 39261648, 2024). "Based on our findings, we propose that HNF4α is a highly interesting target for translational studies and therapy in sepsis." (PMID 39261648, 2024). "To investigate the downstream effects of hepatic HNF4α LOF in sepsis, we generated Hnf4aLiver-i-KO mice." (PMID 39261648, 2024). "This strongly suggests that HNF4α is required to support sufficient STAT3 activity in the liver during sepsis." (PMID 39261648, 2024). "Hnf4aLiver-i-KO mice were significantly more sensitive to CLP than control mice (Hnf4aflfl), which emphasizes the critical role of HNF4α in sepsis." (PMID 39261648, 2024). "We generated Hnf4aLiver-i-KO mice to gain a better understanding of the downstream consequences of HNF4α LOF in liver during sepsis progression." (PMID 39261648, 2024). "An HNF4α agonist protects against sepsis at all levels, irrespectively of bacterial loads, suggesting HNF4α is crucial in tolerance to sepsis." (PMID 39261648, 2024). "We propose HNF4α as a promising therapeutic target in sepsis, highlighting the therapeutic potential of the HNF4α agonist NCT for both treatment and prevention." (PMID 39261648, 2024). "We evaluated HNF4α DNA binding in the liver by chromatin immunoprecipitation followed by sequencing (ChIP-Seq) 8 h after sepsis onset." (PMID 39261648, 2024).
Sepsis (continued). "To conclude, our data suggest that HNF4α dysfunction in sepsis prevents an adequate APR towards IL6, potentially compromising liver regeneration and the removal of hemoglobin and heme during hemolysis." (PMID 39261648, 2024). "Specifically, hepatic HNF4α failure in sepsis mediates lipid dysfunction, downregulates several nuclear receptors, including PPARα, and diminishes IL6-mediated acute phase signaling." (PMID 39261648, 2024). "Like CLP mice, analyses using Enrichr and HOMER motifs showed that most of the genes downregulated by sepsis in pigs are controlled by HNF4α (Fig. EV5B,C)." (PMID 39261648, 2024). "These genes are considered constituents of protective pathways that weaken in sepsis due to hepatic HNF4α LOF but can diminish sepsis lethality when activated/overexpressed." (PMID 39261648, 2024). "We show that genetic depletion of hepatic HNF4α enhances sepsis lethality, confirming its critical role in this disease, associated with increased lipid dysfunction, inflammation, and cell death." (PMID 39261648, 2024). "Our findings are expected to significantly impact both the HNF4α field, particularly its role in hepatic acute phase response, and the sepsis field, emphasizing HNF4α as a potential therapeutic target and the HNF4α agonist NCT as a new treatment option." (PMID 39261648, 2024). "To summarize, depleting HNF4α enhances sepsis sensitivity characterized (transcriptionally) by increased lipid dysfunction, inflammation and cell death." (PMID 39261648, 2024). "This failure, characterized by less STAT3 phosphorylation and less APP production mediated by C/EBPβ and STAT3, can be attributed to the HNF4α LOF in sepsis and contributes to the lethality of CLP." (PMID 39261648, 2024). "The data indicate that changes in HNF4α chromatin binding in the liver during sepsis affect mainly H3K27 acetylation, thereby modulating enhancer activity, with little effect on chromatin accessibility." (PMID 39261648, 2024). "CLP and sham samples were clearly separated by principal component analysis (PCA), indicating major changes in the HNF4α ChIP-Seq profile during sepsis." (PMID 39261648, 2024). "Altogether, HNF4α LOF in sepsis downregulates the expression of many nuclear receptors, including PPARα." (PMID 39261648, 2024). "In this study, we identified a new molecule, HNF4A, as a regulator affecting lung injury in sepsis." (PMID 39979267, 2025). "Similarly, hepatocyte nuclear factor 4-alpha (HNF4α), another critical regulator of hepatic metabolism, has been shown to be dysfunctional in polymicrobial sepsis, contributing to metabolic reprogramming and mortality." (PMID 41439929, 2025). "Overall, this research investigated the potential impact of HNF4A on pulmonary injury in sepsis." (PMID 39979267, 2025). "This study discusses the role and mechanism of HNF4A in sepsis-induced lung damage." (PMID 39979267, 2025). "HNF4A promotes M2 macrophage polarization via the NCOA2/GR/STAB1 axis and attenuates acute-phase gene expression, with its activation linked to improved outcomes in models of sepsis." (PMID 41169395, 2025). "This underscores the involvement of HNF4α in tolerance to sepsis." (PMID 39261648, 2024). "On the other hand, genes upregulated in Hnf4aflfl by CLP as well as in Hnf4aLiver-i-KO relative to Hnf4aflfl in sham may be regarded as components of toxic pathways that become more active during sepsis due to the HNF4α LOF (Dataset EV1)." (PMID 39261648, 2024). "Our data and supporting literature indicate that HNF4α may play a role in shaping the epigenetic landscape and regulating transcription in sepsis." (PMID 39261648, 2024). "We hypothesized that HNF4α is redirected in sepsis by binding less to metabolism-related genes and more to genes associated with tissue repair." (PMID 39261648, 2024). "Consequently, HNF4α LOF during sepsis not only leads to metabolic dysfunction but also impairs acute phase signaling." (PMID 39261648, 2024).
Sepsis (continued). "Moreover, different TF motifs were enriched in sham-specific and CLP-specific HNF4α ChIP-Seq and ATAC-Seq regions, suggesting a potential alteration in the HNF4α interactome triggered by sepsis." (PMID 39261648, 2024). "Hence, in sepsis, HNF4α LOF is strongly associated with reduced HNF4α chromatin binding in general, and HNF4α seems to be redirected by binding less to metabolism-related genes and more to genes associated with tissue repair." (PMID 39261648, 2024). "The difference in p-value indicates progressive HNF4α LOF in liver during sepsis." (PMID 39261648, 2024). "Upon sepsis in wild-type mice, HNF4α is shown to lose its function, leading to PPARα reduction." (PMID 39456859, 2024). "The downstream effects of HNF4α failure in sepsis has a strong effect on PPARα levels and consequent PPARα-mediated FFA consumption, as well as on the expression of several other nuclear receptor TFs in the liver, such as Liver X receptor-α (LXRα), RXRα and Farnesoid X receptor (FXR)." (PMID 39261648, 2024). "In these HNF4α knockout mice, PPARα expression and activity are low, and blood free fatty acid levels and hepatic lipid content are further increased in the context of sepsis." (PMID 39261648, 2024). "Our data suggest that the loss of hepatic HNF4α impairs the expression of several other nuclear receptors besides PPARα, including RXRα, FXR, CAR, AR and LXRα, and therefore has a broad downstream impact in sepsis." (PMID 39261648, 2024). "Additionally, we show that CAR DNA binding is impaired, and we propose that HNF4α may regulate chromatin accessibility of CAR binding sites in sepsis." (PMID 40904458, 2025). "However, during sepsis, HNF4α LOF primarily manifests at the level of chromatin binding." (PMID 39261648, 2024). "These interactors may dictate the function of HNF4α in sepsis, or vice versa." (PMID 39261648, 2024). "Whether HNF4α regulates IL6-mediated APR in sepsis directly or indirectly requires further study." (PMID 39261648, 2024). "However, more research is needed on the mechanism by which HNF4α chromatin binding is changed and the effect of HNF4α dysfunction on other liver metabolic pathways, such as gluconeogenesis and bile acid metabolism in sepsis." (PMID 39261648, 2024). "Importantly, the HNF4α agonist NCT provides protection in sepsis across all these mentioned levels." (PMID 39261648, 2024). "Overall, this study revealed that the regulatory axis of HNF4A/NCOA2/GR/STAB1 affects macrophage polarization, thereby improving sepsis-induced lung damage." (PMID 39979267, 2025). "In this study, hepatocyte-specific HNF4α knockout mice displayed reduced expression and activity of PPARα, diminished IL6-induced acute phase response, and increased mortality from sepsis." (PMID 40061452, 2025). "The mouse model of sepsis was constructed by CLP induction to verify the situation of lung injury and changes in HNF4A expression." (PMID 39979267, 2025). "However, the role of HNF4α in sepsis and in the regulation of PPARα in sepsis remains unknown." (PMID 39261648, 2024). "Our data suggest that HNF4α is required for a proper IL6-mediated APR, which appears to be diminished during sepsis despite elevated plasma IL6 levels." (PMID 39261648, 2024). "HNF4αKO RNA-Seq data from liver already suggested HNF4α failure upstream of FFA oxidation and VLDL secretion problems in sepsis." (PMID 39261648, 2024). "Here, the HNF4α LOF was not limited to the mouse CLP model, but was also observed in porcine sepsis and in human hepatocytes in a humanized mouse sepsis model." (PMID 39261648, 2024). "In that regard, activating HNF4α to enhance Nr1i3 transcription and CAR activity may be a more beneficial therapeutic approach in sepsis." (PMID 40904458, 2025). "HNF4α dysfunction also interferes with interleukin 6 (IL6)-induced, C/EBPβ and STAT3 controlled induction of APR genes and proteins, and hence interferes with liver regeneration in lethal sepsis." (PMID 39261648, 2024).
Sepsis (continued). "The decreased expression of PPARα in Hnf4aLiver-KO mice has been documented, yet the relation between HNF4α and PPARα in sepsis has not yet been described." (PMID 39261648, 2024). "While the PGC1α activator ZLN005 improves survival in polymicrobial sepsis, its impact on HNF4α is not yet understood." (PMID 39261648, 2024). "Our data further suggest that during sepsis, FFA metabolism is changed, mainly at the level of FFA oxidation and lipoprotein secretion, and that PPARα expression is downregulated, both of which can be attributed to the LOF of hepatic HNF4α." (PMID 39261648, 2024). "Moreover, HNF4α DNA binding was reduced in Hnf4aLiver-i-KO samples and in CLP relative to sham 8 h post-CLP (Fig. EV1B,C), suggesting that HNF4α is likely modified in sepsis, potentially through post-translational modifications or altered interactions with cofactors." (PMID 39261648, 2024). "Hence, HNF4α LOF may contribute to problematic FFA oxidation and VLDL secretion, perturbations in bile acid metabolism and cholesterol homeostasis, as well as the inflammatory cascade and cellular damage frequently encountered in sepsis." (PMID 39261648, 2024). "HNF4α and PPARα are known regulators of Nr1i3 transcription, but their link with CAR in sepsis has not been described." (PMID 40904458, 2025). "To elucidate the pathways contributing to the increased sepsis lethality in Hnf4aLiver-i-KO mice, we also identified the genes downregulated and upregulated in CLP in the absence of HNF4α in hepatocytes." (PMID 39261648, 2024).
type 1 diabetes (11 papers, 2009 to 2025). "Among 1021 Chinese individuals with non‐type 1 diabetes in the training dataset, 19 (1.9%) individuals carried pathogenic or likely pathogenic variants in GCK (n = 6), HNF1A (n = 9), HNF1B (n = 3), or HNF4A (n = 1) genes." (PMID 40966384, 2025). "Because PSP/reg1A levels have been shown to be elevated in HNF1A-MODY as well as type 1 diabetes patients, this suggested that PSP/reg1A levels may be negatively regulated by HNF4A." (PMID 23803251, 2013).
macrosomia (9 papers, 2014 to 2025). "Fifty-six percent of HNF4A mutation carriers have been reported to have macrosomia that always occurs in neonatal HH." (PMID 37711893, 2023). "As there is a very high risk of macrosomia in HNF4A pregnancies if the fetus is affected, achieving excellent glycaemic control is essential." (PMID 28556992, 2017). "Recently, HNF4A mutations have been shown to cause macrosomia and hyperinsulinaemic hypoglycaemia (transient and persistent) in early life." (PMID 24299156, 2014). "There is an elevated risk of macrosomia in GCK-MODY, should the fetus lack the GCK mutation from the mother, and in HNF4A-MODY, should the fetus possess the HNF4A gene mutation from the parents." (PMID 39902162, 2024). "Macrosomia and persistent neonatal hypoglycaemia are reported in 54% and 15% of HNF4A genotype positive offspring respectively with a median increase in birthweight of 790 g." (PMID 38933924, 2024). "In the same group, the incidence of macrosomia was four times higher in HNF4A carriers compared to the non-mutation family members (56% vs. 13%, p < 0.001)." (PMID 38933924, 2024). "Heterozygous mutations in HNF4A were known to cause macrosomia but not with HNF1A." (PMID 39421536, 2024). "HNF4A- and HNF1A-MODY affected pregnancies require increased surveillance for foetal macrosomia in utero and neonatal hypoglycaemia soon after delivery." (PMID 38933924, 2024). "A paternal history of HNF4A-MODY warrants the same frequency of assessment of foetal growth in utero, i.e., serial growth assessments are performed from 28 weeks’ gestation at two weekly intervals to detect developing macrosomia." (PMID 38933924, 2024).
mucinous adenocarcinoma (9 papers, 2017 to 2026). An invasive adenocarcinoma composed of malignant glandular cells which contain intracytoplasmic mucin. "Thus, examining the status of HNF4α expression is important for not only assuming the etiology and gene mutational status but also predicting the prognosis in non-mucinous adenocarcinomas." (PMID 38710944, 2025). "Moreover, TTF-1-negative and HNF4α-positive non-mucinous adenocarcinomas showed wild-type EGFR and frequent SMARCA4 loss, and tended to show a high-grade solid morphology and very poor prognosis." (PMID 38710944, 2025). "HNF4α expression was found not only in mucinous, enteric, and colloid adenocarcinomas but also in morphologically conventional non-mucinous adenocarcinomas." (PMID 38710944, 2025). "Approximately half of the HNF4α-positive non-mucinous adenocarcinomas were TTF-1-positive (7/15, 47%), and they frequently showing papillary predominant histology (6/7, 86%)." (PMID 38710944, 2025). "All cases of mucinous, enteric, and colloid adenocarcinoma were HNF4α-positive, TTF-1-negative, and SMARCA4 retained, and showed a high frequency of KRAS mutations (10/18, 55.6%) and no EGFR mutations (0/18, 0%)." (PMID 38710944, 2025). "We found that in grade 3 non-mucinous adenocarcinomas (n = 56), sex, pleural invasion, pStage, HNF4α expression and MUC5AC expressions, were poor prognostic factors (Online Resource 6a)." (PMID 38710944, 2025). "As expected, the squamous marker Trp63 and the mucinous adenocarcinoma marker Hnf4a exhibited enrichment in LUSCs and LUADs, respectively." (PMID 41214366, 2025). "In this study, HNF4α-positive poorly differentiated (grade 3) non-mucinous adenocarcinomas were aggressive phenotypes and showed the worst prognosis, and HNF4α expression was an independent prognostic factor in grade 3 non-mucinous lung adenocarcinomas." (PMID 38710944, 2025). "In conclusion, a subset of HNF4α-positive adenocarcinomas, such as mucinous adenocarcinomas with gastrointestinal differentiation, are TTF-1-negative and SMARCA4 retained, often showing KRAS mutations." (PMID 38710944, 2025). "Histopathologic analysis of controls showed that the lungs contained mucinous adenocarcinoma that expressed HNF4α and the expected pattern of FoxA1/2." (PMID 30475207, 2018). "Although HNF4α-positive grade 3 non-mucinous adenocarcinomas frequently showed the loss of SMARCA4 (2/6, 33%), it was not identified as a poor prognostic factor (Online Resource 6a)." (PMID 38710944, 2025). "A previous study that examined the expression of HNF4α and mucin profiles in lung mucinous adenocarcinomas reported that HNF4α induced the expression of MUC3 in KRAS-mutated mucinous adenocarcinomas, which is a poor prognostic factor for mucinous adenocarcinomas of the breast and appendix." (PMID 38710944, 2025). "Here, we have shown that HNF4α expression was not limited to mucinous, enteric, or colloid adenocarcinomas, which showed gastrointestinal morphology, but also appeared in morphologically conventional non-mucinous adenocarcinomas such as acinar, papillary, and solid adenocarcinomas." (PMID 38710944, 2025). "Mucinous adenocarcinomas associated with thymic cysts have been sporadically reported among primary anterior mediastinal adenocarcinomas; however, no prior reports have documented the correlation with HNF4α." (PMID 38627639, 2024). "For instance, a t-SNE cluster enriched for KRAS-mutant cases exhibited high expression of both HNF4A and MUC5AC, which are expressed at high levels in invasive mucinous adenocarcinoma, a distinct histological subtype of LADC18." (PMID 41198678, 2025). "A gene signature of invasive mucinous adenocarcinoma of the lung, which includes transcription factors (FOXA3, SPDEF, and HNF4A) and mucin proteins (MUC5AC, MUC5B, and MUC3) has been identified." (PMID 36860703, 2022).